ALB (albumin)
Diseases named in the same sentence as ALB in open-access papers (continued):
Sharing a sentence is not in itself a finding about the gene and the disease.
Hyperglycemia (continued). "Recently, mortality in CA patients has been gradually found to be associated with an anion gap, albumin-corrected anion gap, INR, and the stress hyperglycemia ratio, which reflects tissue hypoxia, abnormalities in the coagulation–fibrinolysis system, and electrolyte disturbances." (PMID 39839831, 2024). "We also observed that HCT increases the albumin secretion both at normoglycemia and hyperglycemia." (PMID 39025915, 2024). "The increased concentrations of total proteins and albumin in the sera of the rats administered GA or its combination with GBL could be attributed to attenuate hyperglycemia by GA or its combination with GBL, leading to decreased protein catabolism." (PMID 38324798, 2024). "Hyperglycemia triggers damage to podocytes, leading to albumin excretion and DN progression." (PMID 36771740, 2023). "The hemodialysis duration of 8 ~ 21 years, having hypotension during last hemodialysis, having hyperglycemia on the latest hemodialysis night, disturbance of potassium metabolism, and serum albumin < 35 g/L were the predictors for hypoglycemia during hemodialysis of the patients." (PMID 37833779, 2023). "In preterm infants, glycated albumin (corrected; %) represented hyperglycemia well and could be a valid short-term GCI for glucose monitoring in preterm infants." (PMID 37760819, 2023). "However, both hyperglycemia and serum minimal albumin values are independent protective factors for PJP patients in our study." (PMID 36552932, 2022). "Chronic hyperglycemia induces oxidative stress that impairs endothelial function and podocytes, leading to impaired glomerular filtration barrier, glomerular hyperfiltration, and increased albumin excretion." (PMID 34135862, 2021). "Albumin is the main glycation-modified serum protein in DM, which is attributed to its high concentration in the circulation and 59 lysine residues in its structure, which makes its modification favorable during hyperglycemia and postprandially." (PMID 34684632, 2021). "In addition, the PSP content was high in peony seed and the primary composition was albumin and globulin with good solubility and some potential function for the remission of hyperglycemia." (PMID 33274214, 2020). "We showed that both high glucose and glycated albumin caused an overexpression of MSTN and its receptor in human proximal tubular cells, suggesting that the hyperglycemic milieu per se or downward signals produced by hyperglycemia induce tubular MSTN." (PMID 32286342, 2020). "The systolic BP, and levels of albumin, urea, uric acid, serum creatinine, urine protein and cholesterol were higher in the DN group than in the non-DN group (P < 0.05), which indicated the damage inflicted on the kidneys by hyperglycaemia." (PMID 31349216, 2019). "Previous investigators have proposed that since hyperglycemia can accelerate urinary albumin excretion, the influence of antidiabetic medications on albuminuria may still partly depend on their glucose-lowering capacity." (PMID 31627406, 2019). "Chronic blood hyperglycemia may result in the glycosylation of albumin, which has been confirmed to promote the production of TFPI in endothelial cells and monocytes." (PMID 28716011, 2017). "In conclusion, our results suggested that MDG-1 has a renoprotective effect via reduction of hyperglycemia, which attenuates the concentration of serum albumin and down-regulates the expression of TGF-β1 and CTGF in diabetic glomeruli, consequently decreasing ECM deposition in renal tissues." (PMID 26393572, 2015). "Six weeks after injecting the low dose of streptozotocin, HFD-fed rats (n = 40) showed hyperglycemia with average blood glucose level over 16.7 mmol/L, polyuria with 1.5-fold increased urine volume, and albuminuria with urinary albumin excretion rate higher than 30 mg/24 h." (PMID 25918729, 2015).
Hyperglycemia (continued). "At the end of the study (12 weeks of hyperglycemia + 8 weeks of antibody treatment) urinary albumin levels were 410 ± 96 μg/mg creatinine in the vehicle-treated diabetic rats compared to 170 ± 32 μg/mg creatinine in the antibody-treated group and 204 ± 33 μg/mg in the nondiabetic group." (PMID 25389530, 2014). "Further in vivo studies revealed that compound 10 significantly reduced hyperglycemia by increasing levels of serum insulin, total protein, and albumin, while the fasting blood glucose, body weight and food intake were restored much closer to those of normal rats." (PMID 25153871, 2014). "Glucose concentration is constant in blood in normal condition but it can be changed via hypoglycemia and hyperglycemia (as diabetic condition), therefore, denaturation of human serum albumin is studied in this assay in the presence of various concentration of glucose." (PMID 24250587, 2013). "Glycated albumin (GA) is an Amadori product used as a marker of hyperglycemia." (PMID 21470398, 2011). "This could reflect the fact that in diabetic subjects other factors including hyperglycaemia may influence the day-to-day variation in albumin excretion." (PMID 17183695, 2006). "Therefore, urinary protein and urinary albumin were found to have significantly increased 4 weeks after the onset of hyperglycemia, which was accompanied with typical pathological changes of DN such as mild cortical tubular epithelial cell vacuolar degeneration and tubular basophilic degeneration." (PMID 32266256, 2020). "Furthermore, besides mimicking the function of acarbose, baicalein also could treat hyperglycemia via the inhibition of bovine serum albumin (BSA) glycation." (PMID 33276419, 2020). "They found that hyperglycemia was related to increased ischemia-modified albumin, advanced oxidation protein products, and prooxidants-antioxidants balance concentrations, and an increase in glucose concentrations during glucose loading could cause tissue damage by increasing oxidative stress." (PMID 31655528, 2019). "The most common laboratory findings among confirmed cases were thrombocytopenia (10/12, 83.3%), high AST (8/10, 80%), hyperglycemia (11/13, 84.6%), high bilirubin (6/8, 75%), high BUN (8/13, 61.5%), high ALT (6/10, 60%), and low albumin (5/9, 55.6%)." (PMID 40880888, 2025). "Compared to the normal blood glucose group, patients in the hyperglycemia group exhibited significantly elevated BNP levels (p = 0.036) and reduced albumin levels (p = 0.002)." (PMID 41348723, 2025). "It was found that higher levels of ACAG had a significant correlation to hyperglycemia, insulin, HOMA-IR, HbA1c, total cholesterol, triglycerides, CRP, urine albumin/creatinine and eGFR at baseline (all P<0.05)." (PMID 39574951, 2024). "In STZ-NA-induced rat in this experiment, abnormal hepatic glycogen accumulation and chronic hyperglycemia led to elevated liver enzyme activities of AST and ALT, as well as a significant decrease in albumin content." (PMID 39728311, 2024). "We observed a stable albumin secretion at low HCT conditions, both in hyperglycemia and in normoglycemia, while a high HCT concentration increased albumin secretion over time at both glucose concentrations." (PMID 39025915, 2024). "It notably improves diabetic retinopathy and hyperglycemia by modulating multiple pathways such as inhibition of excess AGE and carbonyl group production, glycation, and thiol group depletion in bovine serum albumin." (PMID 39519546, 2024). "The NFS calculation incorporates BMI, age, hyperglycaemia, AST/ALT ratio, albumin, and platelets, and was initially developed for 733 patients with biopsy-proven NAFLD." (PMID 38809396, 2024). "Compared with wild type mice, PT‐PRDM16‐KO mice had higher kidney to body weight ratio (KW/BW) and urinary albumin/creatinine ratio (ACR) levels at 12 weeks after STZ induction, although they had similar levels of hyperglycemia." (PMID 38072665, 2024).
Hyperglycemia (continued). "In this study, a significantly higher urine albumin-to-creatinine ratio (UACR), hyperglycemia, and an increase in body weight, LDL-C and TC in db/db mice suggested that the animals developed DN." (PMID 34925317, 2021). "Hyperglycemia is recognized as a key initiation factor of ESRD in diabetic patients, which contributes to the increased albumin leakage across the GFB61." (PMID 31409793, 2019). "Meanwhile, Lamp2y/− rats also displayed abnormalities of metabolic function with hypercholesterolemia (CHOL 5.21 ± 0.98 mmol/L) and hyperglycaemia (GLU 9.11 ± 1.57 mmol/L), but total protein (TP) and albumin (ALB) were intact." (PMID 29720683, 2018). "This drug, without affecting hyperglycemia, prevented the onset of hyperfiltration, the increase of the albumin to creatinine ratio (ACR), the reduction of the creatinine clearance, and the lowering of the urinary pH." (PMID 40938394, 2025). "Hyperglycemia, age, smoking, white blood cell count (WBC), uric acid (UA), creatinine (Cr), ALB, and aspartate aminotransferase (AST) were also identified as independent predictors of mortality in multivariate analyses during the follow-up years, according to NHANES data." (PMID 41348723, 2025). "Hyperglycemia (HbA1c>7%) activates the NLRP3 inflammasome, leading to increased IL-6 secretion from monocytes, reduced efficiency of serum albumin synthesis, and a positive correlation between the homeostasis model assessment of insulin resistance (HOMA-IR) and NLR." (PMID 40831574, 2025). "Both glycated albumin and fructosamine on other circulating proteins can be measured for assessment of hyperglycemia in settings where HbA1c testing is not available." (PMID 39589852, 2024). "Knockdown of TRPA1 did not affect hyperglycemia, but it increased kidney to body weight ratio (KW/BW) and urinary albumin/creatinine ratio (ACR) levels." (PMID 38072665, 2024). "To date, acute hyperglycemia has been quantified using several parameters like stress hyperglycemia ratio (SHR), admission blood glucose (ABG), fasting plasma glucose (FPG), ABG to glycated albumin index and triglyceride glucose index." (PMID 39247028, 2024). "Nevertheless, the levels of glycated albumin in pregnant women with hyperglycemia were much greater compared to pregnant women without hyperglycemia." (PMID 38540749, 2024). "All immunological biomarkers (ferritin, LDH, CRP, procalcitonin, IL-6, and CRP/ALB), coagulation biomarkers (aPTT, D-dimer, fibrinogen, PT, and INR), and hyperglycemia biomarkers (random glucose and HbA1c) were significantly higher in the severe patients compared to the other severity groups." (PMID 37448393, 2023). "SeNP and/or BV treatments improved the deleterious effects induced with STZ administration by improving the serum insulin concentrations, which resulted in decreasing the hyperglycemia, decreasing the serum BUN, creatinine and CRP while increasing the serum albumin concentrations." (PMID 36984840, 2023). "During persistent hyperglycemia, glucose forms covalent bond with proteins through nonenzymatic reaction leading to the production of glycated proteins such as glycated albumin and glycated hemoglobin." (PMID 35388310, 2022). "In this study, the renal protection of CR during hyperglycemia was successfully demonstrated by the suppression of NAG (P < 0.05) and BUN (P < 0.05) in the urine, ALB in the serum (P < 0.01), and PKA (P < 0.05) and 6-keto-PGF1α (P < 0.05) in the kidneys of db/db mice after 8-week administration." (PMID 32425787, 2020). "In fact, we found a significant reduction of renal chymase activity using a specific chymase inhibitor, which prevented the augmentation of urinary albumin excretion without reducing hyperglycemia in db/db mice." (PMID 33050674, 2020). "High uric acid hematic disease, plasma albumin levels, intra-aortic balloon pump, number of stents, and hyperglycemia are not included in the final prediction model." (PMID 29950662, 2018).
Hyperglycemia (continued). "As with hypoglycemia, hyperglycemia did not affect albumin and urea secretion as compared to a normoglycemic control." (PMID 27312339, 2016). "Among the independent variables revealed by multivariate logistic regression analysis, low serum albumin, postreperfusion syndrome, intraoperative hyperglycemia and CNI use without combined MMF use were notable as potentially modifiable risk factors." (PMID 26302370, 2015). "This group was of older age had higher BMI, lower levels of HDL-C, and lower serum albumin compared with the group of patients without hyperglycemia." (PMID 21960993, 2012). "Notably, two-way ANOVA revealed a relevant interaction between hyperglycemia and renal IR on the creatinine plasma level and urinary albumin (creatinine, p = 0.018; urinary albumin, p = 0.034), but not on the plasma urea level (urea, p = 0.554)." (PMID 34561469, 2021). "However, it should be noted that the actual degree of hyperglycemia in KK/Ay mice, judging from blood sugar and glycated albumin levels, was not significantly altered by febuxostat administration." (PMID 31546603, 2019). "In patients with C-CH, however, TP and ALB were lower in patients with than without hyperglycaemia." (PMID 28860506, 2017). "However, the serum biochemical analysis showed that C66 treatment for 2 months significantly decreased the levels of the serum creatinine, serum ALB (Alb) and serum total protein (STP) induced by hyperglycaemia (P < 0.001), indicating that C66 administration attenuated the indexes of DN in mice." (PMID 24330074, 2014). "Finally, we treated diabetic mPGES-1 KO mice with a selective COX-2 inhibitor celebrex and found that inhibition of COX-2 significantly reduced the kidney PGE2 content, as well as the urinary albumin level, without affecting the hyperglycemia." (PMID 24984018, 2014). "Additionally, in our study, the non-alcoholic fatty liver disease patients with hyperglycemia had lower levels of serum albumin compared with those without hyperglycemia, although this difference was not independent of age, BMI, and HDL-C." (PMID 21960993, 2012). "However, during hyperglycemia LPS could not stimulate ALB expression further and ALB expression decreased slightly compared to the model group, which needs to be studied deeply." (PMID 37467292, 2023). "In preterm babies with hyperglycemia on the NICU, should intravenous administration of insulin be proceeded by priming of the intravenous system, adding of albumin, or non-priming to get a stable insulin dose?" (PMID 36542240, 2022). "Hyperglycemia is mediated by cytokines, growth factors, and nonepigenetic mechanisms, the latter of which are also some of the key drivers of DKD, involving Wnt/β-catenin signaling, ER stress, excessive ROS, RAAS activation, albumin overload, and the additional production of inflammatory elements." (PMID 34769288, 2021). "WSJPR could improve serum total protein (TP) and albumin (ALB), reduce the excretion rates of urine-TP (U-TP), urine-ALB (U-ALB) and urine urea nitrogen (UUN) (P < 0.05), although it did not significantly alter the hyperglycemia." (PMID 31362740, 2019).
depression (215 papers, 2006 to 2026). "In the ECC subgroup, receipt of radiotherapy and lower albumin levels were independently associated with increased depression risk." (PMID 41618318, 2026). "Bootstrapped mediation models (5000 iterations) indicated that albumin showed a partial statistical mediation pattern in the association between gender and depression, whereas calcium demonstrated a similar pattern for anxiety." (PMID 41463102, 2025). "In those with depression, lower serum albumin levels have been linked to higher depressive symptoms and increased mortality risk." (PMID 40718002, 2025). "Elevated levels of inflammatory cytokines can damage synapses, reduce synaptic density and function, and impair brain neuroplasticity, thereby increasing the risk of depression Albumin possesses anti-inflammatory and immunomodulatory properties." (PMID 40182647, 2025). "Mediating effects of albumin on the relationship of cognitive function and depression scores with the risk of nocturia in females." (PMID 40672414, 2025). "Mediating effects of albumin on the relationship of cognitive function and depression scores with the risk of nocturia in 70–80 years." (PMID 40672414, 2025). "Mediating effects of albumin on the relationship of cognitive function and depression scores with the risk of nocturia in 60–69 years." (PMID 40672414, 2025). "Our results showed a strong association between albumin and nocturia and partially mediate the association between cognitive function/depression and nocturia." (PMID 40672414, 2025). "Albumin and calcium exert protective inverse effects on all affective domains, whereas β2-microglobulin demonstrates a direct positive association with depression and, to a lesser extent, anxiety." (PMID 41463102, 2025). "Several factors, including glycemic control (HbA1c), economic status (PIR), kidney function (albumin-to-creatinine ratio), and psychological health (depression prevalence), were significantly associated with DR." (PMID 40290656, 2025). "Mediating effects of albumin on the relationship of cognitive function and depression scores with the risk of nocturia in males." (PMID 40672414, 2025). "Pruritus was linked to female sex, lower serum albumin levels, and depression, whereas fatigue was independently associated with type 2 diabetes, depression, and nervous system disorders." (PMID 40293122, 2025). "Evidence indicates that low albumin levels are linked to a heightened risk of cardiovascular disease, which is closely related to depression incidence." (PMID 39421614, 2024). "According to the findings of this research, decreased serum albumin levels in Jordanians are associated with an increased odds ratio of depression." (PMID 37880606, 2023). "Low serum albumin levels have been linked to depression symptoms in people who had recent suicide attempts and those suffering from several mental diseases such as acute episodes of mania, and schizophrenia." (PMID 37880606, 2023). "In this study, we identified depression, plasma albumin, and NIHSS score at admission as independent risk factors for the occurrence of persistent PSCI in the 6-month time course." (PMID 37881309, 2023). "Albumin levels were shown to have a significant inverse association with depression (OR = 0.96, P value = 0.001), as determined by the results of the univariate logistic regression analysis." (PMID 37880606, 2023). "The Beck Depression Inventory score was negatively and strongly associated with BMI and moderately and negatively associated with albumin levels." (PMID 36703643, 2023). "Our study revealed an inverse association between serum albumin and depression in CLD patients and this association differed according to liver histological changes." (PMID 34983435, 2022). "Serum TP, albumin, and globulin levels in patients with major depressive disorders are significantly lower than those in healthy controls (HCs), and the reductions of serum TP and albumin levels are closely implicated in the severity of depression." (PMID 35958662, 2022).